RN7SKP134 (RN7SK pseudogene 134)
Gene: Miscellaneous RNA gene on chromosome 12 (14,553,702 to 14,553,970, reverse strand). Ensembl gene ENSG00000200830.
Homologues: Orthologues: chimpanzee 7SK (98% identical), guinea pig 7SK (72% identical). Paralogues in human: RN7SKP255 (84% identical), RN7SKP203 (84% identical), 7SK (83% identical), RN7SKP176 (83% identical), RN7SKP9 (82% identical), RN7SKP90 (82% identical), RN7SKP180 (82% identical), RN7SKP231 (82% identical), RN7SKP37 (82% identical), RN7SKP71 (82% identical), RN7SKP79 (82% identical), RN7SKP1 (81% identical), and 284 more.